ENSG00000288880 (novel transcript)
Synonyms: LOC112268239
Gene: Long non-coding RNA gene on chromosome 1 (150,629,811 to 150,637,743, forward strand). Ensembl gene ENSG00000288880.
Gene Ontology:
Biological process: SRP-dependent cotranslational protein targeting to membrane, signal sequence recognition
Cellular component: signal recognition particle, endoplasmic reticulum targeting